BCL2 (BCL2 apoptosis regulator)
Diseases named in the same sentence as BCL2 in open-access papers (continued):
Sharing a sentence is not in itself a finding about the gene and the disease.
infection (continued). "In a parallel experiment, the level of expression of endogenous Bax and Bcl-2 after infection of HeLa cells with NDV was assessed by qRT-PCR, but no statistically significant change was observed." (PMID 21810274, 2011). "However the effect of both these cytokines on Bcl-2 and IL-7Rα expression in CD8+ T cells during acute phase of infection remains understudied." (PMID 20520779, 2010). "Following confirmation of long-term survival of HFH within Bcl-2-HUVEC gels, we next studied whether engrafted HFH would support infection of the tissue tropic HCV Jc1 isolate in vivo." (PMID 20376322, 2010). "Taken together, the lack of complementation by Bcl-2 at any time point after infection indicates that NF-κB signaling likely provides a role distinct from peripheral B-cell survival during γHV68 latency." (PMID 17257062, 2007). "Using N2A cells stably expressing mutant form of Bcl-2, it has been described that Bcl-2 regulates the induction of apoptosis mediated by endoplastic reticulum (ER) stress rather than by mitochondrial dysfunction after PrPSc infection." (PMID 17573907, 2007). "Additionally, our patient population showed no strong correlation between BCL-2 status and infection rates or response to frontline therapies beyond hypomethylating agents." (PMID 40699745, 2025). "The reporter assays revealed that wild-type VS-Meq had a lower transrepression on the promoter of pp38, which is a viral antigen expressed in the cytolytic infection, whereas it did not affect the transactivation activities of the promoters of meq and bcl-2, an anti-apoptotic molecule." (PMID 38275925, 2024). "In contrast, SeAx cells, in which the 50% TCID of the virus could not be determined on day three after infection, were shown to be Bcl-2-overexpressing." (PMID 39123440, 2024). "The efficient infection of immature and transitional B-cells, but not other B-cell populations, requires the presence of M11, and M11 mimics the function of the endogenous pro-survival Bcl-2 proteins." (PMID 38932171, 2024). "In this study, at the 5th week after infection, the parasite load of undernutrition 65% + infection group in the spleen was the lowest, the expression of PD-1, PD-L1 and Bax in the spleen of this group was downregulated, and TCR, Bcl-2 and TLR4 were upregulated." (PMID 38185681, 2024). "The qPCR results demonstrated that in a comparison of the PBS group (the blank control group consisted of untreated cells) with the mimic NC group, no changes were observed in the transcription levels of Bcl2 and Pten, indicating that the infection process had no impact on the IPEC-JE cells." (PMID 37381058, 2023). "Nonetheless, we also observed that the ratio between the anti-apoptotic BCL2 and pro-apoptotic BAX genes was significantly increased in SARS-CoV-2 infected iPSC-MNs, suggesting that programmed cell death is somehow prevented following infection in these neuronal cells." (PMID 38116398, 2023). "Here, the rSsAKs increased Bcl-2 and Bcl-xl transcription levels and the Bcl-2/Bax ratio, which indicated that the rSsAKs promoted PBMC proliferation and inhibited PBMC apoptosis, thereby promoting cell survival and limiting S. scabiei proliferation in early infection." (PMID 36451837, 2022). "Therefore, this study continued to detect the expression of Bcl-2, and the results showed that the expression of Bcl-2 protein was significantly decreased, indicating that DTMUV infection can inhibit the expression of the antiapoptotic protein Bcl-2 to promote apoptosis." (PMID 35799206, 2022). "Compared with the CON group, NE infection increased (P < 0.05) the number of jejunal TUNEL-positive cells and apoptotic index and mRNA expressions of ileal Bax and jejunal caspase-3, while it reduced the mRNA levels of jejunal Bcl2, indicating remarkable activation of jejunal apoptosis." (PMID 35387091, 2022).
infection (continued). "In the case of doxorubicin (5 μM), we did not observe any differences between the EV and FV groups, so changes may have only been the effect of infection (C vs. EV: p < 0.05), rather than a combination of Bcl-2 and BDNF overproduction (EV vs. FV: ns)." (PMID 34209365, 2021). "Infection with MAP or MTB did not exhibit significant changes in Bcl2 (MAP: 2.33 ± 0.18, MTB: 1.50 ± 0.29; p < 0.05) while adding nicotine treatment following mycobacterial infection elevated its expression (MAP + nicotine: 4.60 ± 0.11, MTB + nicotine: 5.71 ± 2.26; p < 0.05)." (PMID 34070119, 2021). "However, at day 5 post infection, the proliferation rate of Tbx21−/− SMARTA TFH cells dropped quickly to a significantly lower level than that of WT cells, which was consistent with the lower Bcl2 expression in Tbx21−/− SMARTA TFH cells." (PMID 30984183, 2019). "This suggests that particular tissues may be more prone to infection; however, this aspect and the observation that expression patterns of pro-apoptotic Bcl-2 proteins vary amongst tissues has not been adequately addressed for the vast majority of viruses." (PMID 28984827, 2017). "Bcl-2 was expressed well and did not reduce the ratio of apoptosis after infection." (PMID 27434587, 2016). "With the exception of cell infection with strain 72, there was no expression of the Bcl-2 gene." (PMID 25299837, 2014). "Moreover, it has been found that during infection with RNA viruses a BH3-like domain of IRF-3 mediates binding to cytosolic Bax (but not Bcl-2, Bcl-XL or Bak) to induce Bax activation, culminating in cytochrome c release and apoptosome formation." (PMID 22935147, 2012). "However, the elimination of maEBOV-induced lymphocyte apoptosis (in bcl-2 transgenic mice) did not protect animals from lethal infection, suggesting that lymphocyte apoptosis is not a major factor in EBOV pathogenesis." (PMID 21994766, 2011). "Taken together, our data suggests that IL-7 and IL-15 have overlapping roles in mediating up-regulation of Bcl-2 and CD127 on antigen-specific CD8+ T cells and that differential CD127 expression does not impede CD44 expression or effector functions during acute phase infection." (PMID 20520779, 2010). "Furthermore, we identify in the current study that Bcl-2, mcl-1, and hsp-70 and-27 are not affected during the entire time course of the infection, supporting the essential role of Bim in the mitochondria, and not other apoptotic proteins, in the context of HIV." (PMID 30850623, 2019). "By contrast, the protein levels of BCL-2, BCl-XL, BAX, BAK, BIM, and BID, as well as mRNA levels of BAX, were not affected by SAMHD1 expression or HIV-1NL4-3 infection of THP-1 cell lines." (PMID 40434097, 2025). "The expression of the pro‐survival molecules CD127 and Bcl2 was examined in EYFP+ cytokine negative CD4 T cells and those expressing IFN‐γ, IL‐2 or TNF 40 days post‐infection." (PMID 37490492, 2023). "A similar expression of bcl2 was observed in 24-h infected samples, unlike infection-III, in which we detected a higher expression of bcl2." (PMID 34585958, 2021). "Our data showed that the levels of p-JNK, p-Bcl-2, LC3-II and DENV2 NS1 proteins evidently increased, but the expression levels of Bcl-2 and BECN1 were not significantly changed at 36 h post DENV2 infection (lane 1 vs. lane 2)." (PMID 29323257, 2018).
infection (continued). "Upon infection with M. bovis BCG, the transcription of Bcl2 was not much affected when compared to NI cells, whereas that of Bax was significantly increased." (PMID 26483789, 2015). "Furthermore, Bcl-2 expression did not protect BHK-21 or AT3-neo cells at later time points, and infection of BHK-21 or AT3-neo cells with SFV replicon vectors or with wild-type SFV4 did not lead to release of cytochrome c from mitochondria." (PMID 17904678, 2008). "Therefore, it is possible that the expression of Bcl-2 may play a role in protecting cells and delays JEV-induced apoptosis, especially in the early stage of infection but not in the later stage of infection." (PMID 31658698, 2019).
hematological malignancies (167 papers, 2014 to 2026). "Evading apoptosis by overexpression of anti-apoptotic Bcl-2 family proteins is a hallmark of cancer cells and the Bcl-2 selective inhibitor venetoclax is widely used in the treatment of hematologic malignancies." (PMID 36658493, 2023). "BCL-2 is an anti-apoptotic protein that is commonly expressed in hematologic malignancies and is associated with tumorigenesis and treatment resistance." (PMID 38001669, 2023). "The over-expression of the Bcl-2 protein is a common feature of many solid cancers and hematological malignancies, and it is typically associated with poor prognosis and resistance to chemotherapy." (PMID 36099249, 2022). "The overexpression of BCL-2 in hematologic malignancies has been associated not only with enhanced cell survival and apoptosis evasion, but also with therapy resistance, especially in leukemic stem cells." (PMID 33251134, 2020). "Taking these into account, targeting BCL2 proteins to cause apoptosis is considered as a potential therapeutic approach in hematological malignancies." (PMID 31253168, 2019). "In hematologic malignancies, the impairment of apoptosis process is often caused by BCL2 overexpression." (PMID 31253168, 2019). "In hematologic malignancies, BCL-2 is often found to be over-expressed or amplified, causing evasion of apoptotic cell death." (PMID 31370269, 2019). "In hematologic malignancies, this impairment of apoptosis is often caused by overexpression of the pro-survival protein Bcl-2." (PMID 29531548, 2017). "Together the data obtained by using different pharmacological inhibitors of Bcl-2 indicated a marked susceptibility of hematologic malignancies towards the Bcl-2-targeting protocols." (PMID 24603326, 2014). "Increases in the expression of the anti-apoptotic protein Bcl-2 are associated with cellular resistance to conventional chemotherapeutic drugs, especially in the case of hematologic malignancies." (PMID 25390937, 2014). "In this review, we listed the drug information of developed BCL-2 inhibitors, elaborated the mechanism of BCL-2 inhibition, briefly described the achieved progress of venetoclax in hematological malignancies, and discussed the indicative genetic mutations that influence the therapeutic effects." (PMID 37894324, 2023). "In addition, venetoclax has limited use in solid tumors because BCL-2 upregulation is mainly associated with the survival of hematologic malignancies and is unimportant for the survival of most of the solid tumors." (PMID 34296214, 2020). "Previous data showed that an imbalanced Bcl-2 protein level causally determines hematologic malignant progression and accordingly targeting the Bcl-2 protein family has been proven to be successful, in particular, in hematologic malignancies." (PMID 24603326, 2014). "Lisaftoclax is a novel, potent, selective BCL-2 inhibitor under clinical development for the treatment of patients with hematologic malignancies or solid tumors and has shown clinical antitumor benefit." (PMID 42130633, 2026). "In contrast, in hematological malignancies, where both Bcl-xL and Bcl-2 are typically expressed at similar levels, both proteins contribute significantly to influencing Bax activation and thereby cell fate." (PMID 40841912, 2025). "The uptake of venetoclax into routine practice highlights the clinical value of targeting the pro-survival BCL2 proteins in hematological malignancies." (PMID 40204951, 2025). "For instance, venetoclax, the first approved BCL-2 inhibitor, has achieved significant progress in treating hematological malignancies." (PMID 40707992, 2025). "ABT-737 and Navitoclax: Due to its dysregulated expression in some hematological malignancies, BCL2 is a promising therapeutic target despite its broad expression in normal cells." (PMID 40113751, 2025). "The therapeutic potential of MCL1 inhibitors, both as monotherapy and in combination with BCL2 inhibitors like venetoclax, is being explored in various hematologic malignancies." (PMID 40075071, 2025).
hematological malignancies (continued). "Selective inhibition of BCL-2 emerged promising for the treatment of BCL-2-dependent hematological malignancies." (PMID 40525911, 2025). "The BCL-2 inhibitor venetoclax (VEN) has emerged as an important therapeutic backbone for hematological malignancies, but secondary resistance is a major challenge." (PMID 41457105, 2025). "Among the candidate therapies, the BCL-2 inhibitor Venetoclax, typically used for hematologic malignancies, emerged as a promising option." (PMID 41301024, 2025). "Venetoclax, the only FDA-approved BH3 mimetic, has demonstrated strong clinical efficacy in treating hematologic malignancies by targeting the anti-apoptotic protein BCL2." (PMID 41155156, 2025). "Although inhibitors targeting BCL-2, such as Venetoclax, have shown efficacy in hematological malignancies, their therapeutic potential in solid tumors remains limited." (PMID 40699886, 2025). "Venetoclax, FDA-approved for hematologic malignancies, selectively targets BCL2, while Navitoclax inhibits BCL2, BCL-xL, and BCL-w." (PMID 40715042, 2025). "In recent years, BCL2 inhibitors have made great progress in the treatment of hematologic malignancies." (PMID 39735667, 2025). "Targeted inhibition of Bcl-2 proteins is a rational therapeutic option for hematological malignancies that are dependent on antiapoptotic Bcl-2 proteins." (PMID 38956026, 2024). "For instance, BCL2 inhibition by venetoclax has emerged as a new treatment approach in various hematological malignancies, underscoring the importance of understanding and overcoming resistance mechanisms." (PMID 39275127, 2024). "Initially, the Bcl-2 family protein, B-cell lymphoma 2-related protein A1 (BCL2A1), with anti-apoptotic function, was reported to interact with pro-apoptotic BCL2 proteins in the hematopoietic tissue and to be highly expressed in hematologic malignancies." (PMID 39768244, 2024). "Although good treatment results for various hematologic malignancies have been obtained with the use of BCL-2 inhibitors, little is known about how these compounds affect immune cells." (PMID 39060763, 2024). "It becomes evident that BCL-2 inhibitors can be used as a novel treatment option in hematological malignancies, however, their expanded use has led to both innate and acquired drug resistance." (PMID 39906657, 2024). "Venetoclax was developed as a BH3-mimetric drug, a highly selective Bcl-2 inhibitor that induces apoptosis in Bcl-2-expressing hematological malignancies." (PMID 38473345, 2024). "Obatoclax has poor efficacy but good tolerance, supporting further research on the use of BCL-2 inhibitors in treating hematologic malignancies." (PMID 39060763, 2024). "One of the most successful BH3 mimetics, venetoclax, a selective BCL2 inhibitor, has proven to be highly effective in the treatment of patients with hematologic malignancies." (PMID 38459020, 2024). "Other potential predictive factors that have been reported in patients with hematologic malignancies include age, use of BCL2 inhibitors, use of JAK2 inhibitors, absolute lymphocyte count, and circulating CD4+, CD8+, and natural killer cell counts." (PMID 37685720, 2023). "Among them, venetoclax is a well-studied BH3 mimetic drug that selectively antagonizes the antiapoptotic protein BCL-2, and its treatment effect is particularly significant in hematological malignancies." (PMID 37894324, 2023). "Induction of apoptosis through targeting Bcl-2 anti-apoptotic proteins is an effective therapeutic strategy for hematologic malignancies, and Bcl-2 inhibitor venetoclax is widely used to treat AML and CLL." (PMID 36658493, 2023). "Targeting the B-cell lymphoma 2 (Bcl-2) family proteins has been the backbone for hematological malignancies with overall survival improvements." (PMID 37720343, 2023).